Y_RNA (Y RNA )
Gene: Miscellaneous RNA gene on chromosome 3 (120,210,320 to 120,210,421, forward strand). Ensembl gene ENSG00000206721.
Homologues: Orthologues: chimpanzee Y_RNA (100% identical), macaque Y_RNA (94% identical). Paralogues in human: Y_RNA (90% identical), Y_RNA (89% identical), RNY3 (88% identical), Y_RNA (88% identical), RNY3P1 (87% identical), Y_RNA (87% identical), Y_RNA (86% identical), Y_RNA (85% identical), Y_RNA (84% identical), RNY3P14 (83% identical), RNY3P16 (83% identical), RNY3P4 (83% identical), and 95 more.